WRN (WRN RecQ like helicase)
Diseases named in the same sentence as WRN in open-access papers (continued):
Sharing a sentence is not in itself a finding about the gene and the disease.
cancer (continued). "In this review, we focus on the roles of RecQ helicases, particularly on the cancer-associated BLM, WRN, and RECQL4, and discuss their potential as targets for cancer treatment." (PMID 35267530, 2022). "In conclusion, the present study establishes the significance of WRN‐mediated removal of TOP1cc and NF‐κB activation in chemoresistance of cancers to physiologically relevant concentration of CPT." (PMID 35582959, 2022). "It has also been shown that WS patient cells or WRN‐depleted cancer cells are hypersensitive to TOP1 inhibitors due to defective S‐phase checkpoint and repair." (PMID 35582959, 2022). "Recent genome-wide screening studies using CRISPR-Cas9 sgRNA libraries have reported that WRN inhibition induces synthetic lethality in cancer cells with high microsatellite instability (MSI)." (PMID 36292687, 2022). "Thus, the dependence of MSI-associated cancers on WRN could be exploited as a therapeutic target." (PMID 35267530, 2022). "Biallelic germline mutations in BLM, WRN, and RECQL4 have been linked to rare cancer-predisposing syndromes." (PMID 35782872, 2022). "Among these five, mutations in BLM, WRN, and RECQL4 are associated with premature aging and a higher risk of developing cancers." (PMID 35267530, 2022). "CRISPR‐Cas9 knockout, shRNA silencing, and under‐expression of WRN confer high‐sensitivity of multiple cancers to TOP1 inhibitor." (PMID 35582959, 2022). "WRN helicase is of interest from a cancer therapy perspective in that it is observed to be highly expressed in rapidly dividing cells and cancer." (PMID 35567571, 2022). "Several studies identified WRN synthetic lethal vulnerability in cancers with microsatellite instability, suggesting specific WRN inhibitors hold great potential to target microsatellite instability tumors to enable a clear stratification path in the clinic." (PMID 35463312, 2022). "Treatment with siRNA for WRN increased sensitivity of cancer cells to CPT-11, a topoisomerase I inhibitor." (PMID 35782872, 2022). "WRN has been identified as being an attractive synthetic lethal target in the setting of microsatellite unstable cancers." (PMID 35782872, 2022). "It has been shown that the WRN promoter is commonly hypermethylated, thereby leading to silencing of WRN expression, in different human cancer cell lines." (PMID 35782872, 2022). "Recently, synthetic lethality between WRN and mismatch repair (MMR) has been identified by several groups, suggesting that WRN can regulate DNA repair pathway mechanisms promoting cancer cell survival." (PMID 36032672, 2022). "Germline mutations in certain DNA helicase genes can cause cancer predisposition syndromes including the Bloom syndrome caused by BLM mutation and the Werner syndrome caused by WRN mutation." (PMID 35855837, 2022). "Nevertheless, in WRN-depleted microsatellite instability (MSI) cancer cells, MUS81 complex shatters chromosomes, which causes apoptosis of cancer cells." (PMID 33791310, 2021). "In other words, WRN was selectively essential for MSI-H cancers, and the inhibition of WRN-induced synthetic lethality in MSI-H cancer models." (PMID 33525614, 2021). "Novel small molecular inhibitors targeting WRN have also been screened out, prohibiting the proliferation of cancer cells." (PMID 34671219, 2021). "Loss of WRN, a DNA repair helicase, was identified as a strong vulnerability of microsatellite instable (MSI) cancers, making WRN a promising drug target." (PMID 33199508, 2021). "BLM, WRN, and RECQL4 are associated with genetic disorders characterized by chromosomal instability, premature aging, and increased susceptibility to cancer." (PMID 33824465, 2021). "The involvement of WRN, BLM, and RecQL4 family members has been determined in the pathogenesis of well-defined genetic disorders with an elevated risk of cancer." (PMID 34164337, 2021). "Here, we demonstrate that WRN helicase ensures efficient restart and limits excessive degradation of stalled forks in BRCA2-deficient cancer cells." (PMID 34772932, 2021).
cancer (continued). "Recently, WRN was identified as a synthetic lethal vulnerability in cancers with microsatellite instability." (PMID 33718381, 2021). "For example, the MSI that often leads to cancer simultaneously makes the inhibition of Werner syndrome ATP-dependent helicase (WRN) lethal to the tumor cells." (PMID 33753749, 2021). "WRN is required to enact a timely restart following replication stalling and limit excessive degradation of stalled forks in BRCA2-deficient cancer cells." (PMID 34772932, 2021). "Attenuation of WRN helicase results in enhanced fork degradation and defective fork restart in BRCA2-mutated cancer cells." (PMID 34772932, 2021). "This agrees with previous reports claiming that downregulation of WRN leads to disrupted redox homeostasis and proliferation impairment in cancer cells." (PMID 34612580, 2021). "Other human helicases, such as BLM and WRN, are also upregulated in multiple tumors, driving cancer cells to rapidly proliferate, supporting oncogenic activation and potentially playing distinct functions in driving DNA replication stress." (PMID 34381789, 2021). "The identification of a role for WRN in regulating mRNA export and protein output has potential implication in cancer therapy." (PMID 33054770, 2020). "Sensitivity to DNA topoisomerase I inhibitors in cancer therapy can be affected by DNA hypermethylation of the Werner (WRN) gene that reduces WRN expression." (PMID 32850327, 2020). "Consistent with the idea that WRN is required for cancer cell proliferation, WRN knockdown suppresses anchorage-dependent growth of cancer cells in vitro and MYC-induced oncogenesis in animal models." (PMID 33054770, 2020). "To gain an understanding of the role of WRN in cancer cell proliferation, we used a conditional shRNAs system to precisely define the early cellular changes induced by WRN depletion." (PMID 33054770, 2020). "Homozygous or compound heterozygous mutations in WRN cause Werner syndrome (MIM# 277700), a rare segmental progeroid syndrome characterized by chromosomal instability and cancer predisposition." (PMID 32585810, 2020). "Since depletion or inactivation of WRN rapidly elicits senescence or apoptosis in many cancer cell types, our data suggest that the regulation of mRNA export by WRN is important to sustain the proliferative potential of these cells." (PMID 33054770, 2020). "In summary, we identified a new partner and a novel function of WRN, which is especially important for the proliferation of cancer cells." (PMID 33054770, 2020). "In this study we investigated the mechanism of translational attenuation by WRN depletion using HeLa cells as a cancer cell model and demonstrate that WRN influences the nucleocytoplasmic distribution of mRNAs." (PMID 33054770, 2020). "In particular, we find that WRN-depleted MSI-H cancer cells display chromosome breaks, chromatin bridges and micronuclei indicative of genome instability that is highlighted during cell division." (PMID 30910006, 2019). "To experimentally corroborate the WRN dependency of MSI-H cancer cells, we applied short-interfering RNA (siRNA)-mediated knock-down of WRN in a panel of three MSS (SK-CO-1, CaCo-2, SW480) and three MSI-H (HCT 116, RKO, SNU-C4) CRC cell lines." (PMID 30910006, 2019). "We observed that two of the newly identified WRN helicase inhibitors inhibited proliferation of cancer cells in a lineage-dependent manner." (PMID 30625228, 2019). "By leveraging recent functional screening data of cancer cell lines we identify Werner syndrome helicase (WRN) as a novel specific vulnerability of microsatellite instability-high (MSI-H) cancer cells." (PMID 30910006, 2019). "Defects in WRN lead to Werner syndrome, which is characterized by premature aging and high cancer incidence." (PMID 31570747, 2019). "RECQL is one of the five RECQ genes, three of which (BLM, WRN and RECQL4) have been implicated in genetic disorders with increased cancer risk." (PMID 30610487, 2019).
cancer (continued). "Molecular defects in the RecQ helicases give rise to genomic instability, and mutations in WRN, BLM, and RECQL4 are linked to hereditary diseases characterized by accelerated aging or associated with cancer." (PMID 29998112, 2018). "It is also of note that loss of “site-associated” genes such as WRN, NOTCH2, MBD1 and PI3KR1 had already been associated to development of human cancer." (PMID 29755661, 2018). "WRN, like other human RecQ helicases, is typically up-regulated in its expression in various cancer cell lines; moreover, their down-regulation by RNA interference has been shown to cause decreased proliferation." (PMID 29998112, 2018). "This alteration is not due to a defect in gene expression nor protein instability, but due apparently to a defect in the proper protein synthesis in WRN‐depleted cancer cells.." (PMID 30584990, 2018). "Accumulating evidence suggests that WRN plays a crucial role in one or more genome stability maintenance pathways, through which it suppresses cancer and premature aging." (PMID 30400178, 2018). "Functional autosomal recessive loss of BLM, WRN and RECQL4, results in hereditary human syndromes characterized by cancer predisposition and premature aging (Bloom's, Werner's, and Rothmund-Thomson's syndromes, respectively)." (PMID 27764811, 2016). "Collectively these results demonstrate that WRN undergoes re-localization in cancer cells treated with CPT." (PMID 26959889, 2016). "Increased WRN expression is observed in several cancer cell lines and depletion of WRN induces cell death in these cells." (PMID 26959889, 2016). "Given that certain HDAC inhibitors are approved or in clinical trials for cancer treatment, it will be informative to assess if WRN-dependent pathways are involved in anti-proliferation." (PMID 25906194, 2015). "RECQL is considered to be genome caretaker, and mutations in three of five RecQ genes, BLM, WRN and RECQ4 are associated with cancer predisposition and/or premature aging." (PMID 25945795, 2015). "Some recent evidences suggest that DNA damage induced by adriamycin enhances the TIGAR and TKTL1 expression and knocking down the TKTL1 or WRN complex both leads to reduced glycolytic metabolism and accumulation of DNA damage in cancer cells." (PMID 25925410, 2015). "Restoration of WRN expression by in vitro demethylation of promotor or by reintroduction of WRN into cancer cells induces tumor-suppressor-like features, such as reduced density of colony formation and inhibition of tumor growth, in mouse xenograft models." (PMID 25620975, 2014). "As expected, the anticancer activity of conventional genotoxic drugs is significantly augmented by combined treatment with RECQL1- or WRN-siRNAs that prevents DNA repair in cancer cells." (PMID 25620975, 2014). "Three of the human RecQ helicase disorders with mutations in WRN, BLM and RecQL4 helicases exhibit premature aging and cancer susceptibility owing to perturbations in DNA replication, transcription, recombination and repair." (PMID 23894508, 2013). "Recent studies have shown reduced WRN expression due to aberrant DNA hypermethylation in cancer cells." (PMID 22797812, 2012). "Methylation of CpG islands in the WRN promoter region is related to carcinogenesis in various cancers." (PMID 22797812, 2012). "Defects in the genes of three of the five human DNA helicases, BLM, WRN and RECQ4, are responsible for distinct genetic disorders associated with cancer predisposition." (PMID 21752281, 2011). "Although this model provides a reasonable description of WRN's mechanistic role during the development of cancer, we are aware of the potential limitations of this study and the need for further studies." (PMID 21267443, 2011). "This suggests that Sirt1 regulates WRN-mediated cellular responses to DNA damage through its deacetylation and can help to prevent cancer." (PMID 21549004, 2011).
cancer (continued). "Contradictorily, WRN deficient human fibroblasts derived from WS patients show a characteristically slower cell proliferation rate, as do primary fibroblasts and human cancer cell lines with WRN depletion." (PMID 21267443, 2011). "Acute depletion of WRN in primary fibroblasts and human cancer cell lines led to marked growth inhibition." (PMID 21267443, 2011). "It is possible that longer T-oligos provide a better substrate for WRN, but additional experiments are required to delineate this point and to optimize the T-oligo as a cancer chemotherapeutic agent." (PMID 17257427, 2007). "It is reported that inhibiting WRN is a potential strategy for microsatellite instability (MSI) cancer therapy.[6a,c] Precise evaluation of WRN inhibitory efficiency in living cells might be promising for WRN inhibitor development." (PMID 39737862, 2025). "Recently, increasing evidence has indicated that WRN is essential in the pathways that maintain genomic stability and may contribute to protection against cancer and premature aging." (PMID 40530580, 2025). "WRN inhibitors sensitize cancer cells to topoisomerase inhibitors and to mitomycin C in FA cells that have defects in repair of interstrand crosslinks, suggesting that WRN may play a role in the repair of these types of lesions." (PMID 39125869, 2024). "Genome-scale CRISPR/Cas9 screening of 324 cancer cell lines from 30 cancer types, developed to provide an effective portfolio of cancer drug targets, has recently identified Werner syndrome ATP-dependent helicase (WRN) as a new candidate synthetic lethal target in microsatellite instability tumors." (PMID 39696697, 2024). "There is a strong correlation between WRN genetic essentiality and sensitivity to pharmacological inhibition, highlighting the compounds' specificity and validating the utility of the cancer dependency map in identifying targets that are therapeutically exploitable." (PMID 38587317, 2024). "Over lunch at the 2011 Aspen Cancer Conference, we found our labs were independently pursuing gene expression profiling analyses in BS and WS patient-derived fibroblasts, and in control fibroblasts acutely depleted of WRN or BLM protein." (PMID 38994931, 2024). "Not only might WRN degraders be more potent in killing MSI cancers, but they could also be used to treat MSI tumours that become resistant to helicase inhibitors." (PMID 39242638, 2024). "Next, we used GRETTA to assess whether cancer cell lines with WRN LOF (WRNLOF) alterations might require KMT2D for survival." (PMID 39578878, 2024). "Finally, the SL interaction between KMT2D and WRN contributes a new layer of understanding in MSI cancer cell vulnerability and potential strategies for identifying patients sensitive to WRN inhibitors." (PMID 39578878, 2024). "Given its promise as a cancer therapeutic target, a deeper understanding of DNA replication and repair regulatory mechanisms for WRN may provide additional insights that can be exploited for therapeutic-based purposes." (PMID 39025847, 2024). "Therefore, WRN represents a promising new synthetic lethal target for developing drugs to treat cancers with MSI." (PMID 39242638, 2024). "This platform could be used, in principle, to carry out genome wide CRISPR screening for alternative targets to WRN that could be used to selectively kill MSI cancer cells." (PMID 39242638, 2024). "Genetic WRN inactivation results in chromosomal defects in MSI cancer cells." (PMID 38587317, 2024). "We suggest that MAT1A and WRN variants and PMS2 loss could contribute to the hereditary cancer predisposition phenotype observed in this family." (PMID 37628631, 2023). "WRN expression was thought to influence the sensitivity of cancer cells to DNA Top I inhibitors." (PMID 37092854, 2023). "WRN contributes to chromosomal stability for survival in both normal and cancer cells." (PMID 37130431, 2023). "Besides, WRN expression is downregulated in multiple cancers in patients due to epigenetic silencing." (PMID 35582959, 2022).
cancer (continued). "For instance, inhibitors of RAD51 and WRN sensitize cancer cells to DNA damaging agents." (PMID 36569948, 2022). "In addition to BLM and WRN, mutations in DDX3X have been associated with several diseases, specifically several cancers, epilepsy, and female intellectual disability." (PMID 35626643, 2022). "We have long pursued the possibility of WRN being a potential anticancer target because we have speculated that some cancer cells depend on WRN for their survival." (PMID 36292687, 2022). "WRN contributes to chromosome stability not only in normal cells but also in cancer cells." (PMID 36292687, 2022). "Recent large-scale silencing screens using CRISPR-Cas9 mediated knockouts and RNA interference in 517 cell lines identified WRN as essential for the survival of cancers with microsatellite instability (MSI) but is dispensable in microsatellite stable (MSS) cancers." (PMID 35267530, 2022). "However, when WRN is inhibited in the MSI cancer cells, the secondary structure of the elongated repeats is cleaved by the MUS81 nuclease, leading to massive chromosome disruption." (PMID 36292687, 2022). "Importantly, multiple studies have identified WRN to be a genetic dependency/synthetic lethal target in cancers with microsatellite instability (MSI), raising the possibility of selective targeting of this subset of cancers by WRN small molecule inhibition." (PMID 35567571, 2022). "Although WRN inhibition in this context might effectively eliminate the cancer cells, full cancer eradication would only ensue if the MSI cells had accumulated sufficient (TA)n repeat expansions to render them WRN dependent before becoming transformed." (PMID 36379964, 2022). "WRN is a key drug target for cancers with microsatellite instability." (PMID 33199508, 2021). "EAC is related to WRN-truncated type mutations that lead to genomic instability in cancers, but not ESCC." (PMID 33826001, 2021). "Furthermore, our observations highlight the ATPase activity of WRN helicase as a therapeutic target to attack MSI-H cancers and the need for a crystal structure of the ATPase core of the WRN helicase domain." (PMID 33199508, 2021). "The observation that many cancer cell types display higher levels of WRN may reflect an increase requirement of mRNA export in these cells, as it is the case for other export proteins." (PMID 33054770, 2020). "When expanding our investigation of other cancer predisposition genes besides ALK and PHOX2B, we detect rare variants such as a nonsense mutation in BARD1 as well as missense variants in CHEK2, BRCA2, and WRN." (PMID 33384420, 2020). "Given that rapidly proliferating cancer cells have an increased requirement of de-novo protein synthesis, our findings provide clues on how WRN may impact the growth of normal and cancer cells differentially." (PMID 33054770, 2020). "However, we cannot rule out that alterations frequently co-occurring with MMR-deficiency or MSI-H status alone or in combination contribute to the context-dependent requirement on WRN function in MSI-H cancer cell lines." (PMID 30910006, 2019). "By leveraging a recently defined map of cancer cell specific vulnerabilities and a comprehensive molecular characterization of cancer cell models we identify WRN helicase as a selective dependency in MSI-H cancer cell lines." (PMID 30910006, 2019). "Also, BLM, the Werner syndrome RecQ like helicase (WRN), and NBS1 are implicated in different types of cancer." (PMID 28471392, 2017). "Although patients with WS develop various cancers, limited studies have been conducted to correlate WRN mutations in cancers in non-WS individuals." (PMID 29043077, 2017). "CPT is an anti-cancer agent which blocks replication and induces WRN degradation." (PMID 29043077, 2017). "Therefore, it will be of great interest to ascertain if FANCJ and other helicases (e.g., WRN) are suitable for modulation in emerging cancer therapies." (PMID 27376332, 2016).